NEDD9 (neural precursor cell expressed, developmentally down-regulated 9)
Diseases named in the same sentence as NEDD9 in open-access papers (continued):
Sharing a sentence is not in itself a finding about the gene and the disease.
tumor (continued). "The results showed that NEDD9 knockdown significantly inhibited the tumor sphere formation capability, which is an in vitro characteristic of self-renewal and proliferation capacities, stemness-related transcription factors, and CSC marker expression." (PMID 33710809, 2021). "In respect to the expression of Cx43 and NEDD9, patients with lymph node metastases showed higher expression of epithelial Cx43 in the primary tumor." (PMID 33485292, 2021). "By co-culturing ESCC cells with G-MDSC, we observed enhanced NEDD9 expression, tumor sphere formation, and expression of stemness-related transcription factors, KLF4 and ALDH1A3." (PMID 33710809, 2021). "The results showed that NEDD9 knockdown reduced the tumor incidence, whereas NEDD9 overexpression in KYSE450 cells increased the tumor incidence." (PMID 33710809, 2021). "Consistent with the results obtained in SP cells, we found that only NEDD9 was upregulated in tumor sphere-forming stem-like cells, when compared to the expression in parent cells." (PMID 33710809, 2021). "NEDD9 overexpression significantly enhanced tumor sphere formation, and also elevated the expression of stemness-related transcription factors, including KLF4 and ALDH1A3." (PMID 33710809, 2021). "NEDD9 expression was correlated with tumor invasion (P = 0.0218), differentiation (P = 0.0153), and poor prognosis (P = 0.0373)." (PMID 33710809, 2021). "In the late stage of tumor progression (day 28), there was a reduction in the levels of Csf1, Mmp14, Nedd9, Nf2, Plaur, and Tgfb1 genes by all the investigated compounds." (PMID 32887237, 2020). "This study was conducted to investigate the serum levels of neural precursor cell expressed developmentally downregulated protein 9 (NEDD9) in patients with PC and the relationship between tumor progression and known prognostic parameters." (PMID 30544746, 2018). "A lung metastasis model of HCC was used to determine the effect of NEDD9 on tumor metastasis in vivo." (PMID 27974675, 2017). "Previous studies reported that Nedd9 is involved in tumor differentiation, migration and metastasis, and therefore, it is also possible that Nedd9 supports osteoclast motility as well." (PMID 27336669, 2016). "Specifically, Nedd9 expression positively correlates with a series of adverse prognostic markers, including high tumour grade and metastatic disease." (PMID 25606587, 2014). "We observed that intracranial injection of GB-NS over-expressing miR-145 delays significantly tumor development: deriving tumors showed a significant down-regulation of NEDD9." (PMID 22869051, 2012). "Recent studies suggest that changes in the expression of NEDD9 were a potent prometastatic stimulus in various tumor cells." (PMID 22984505, 2012). "Given the fact that NEDD9 promotes tumor cell migration and invasion, these results suggest that NEDD9 plays a key role in facilitating MDA-MB-231 cell migration, invasion, and growth." (PMID 22984505, 2012). "The NEDD9 gene, also known as HEF1 and CAS-L, encodes a scaffolding protein that promotes tumor cell migration and invasion, but at the same time inducing apoptosis and mitotic defects that trigger cell cycle arrest." (PMID 21283797, 2011). "Conversely, a null NEDD9 genotype significantly increases the latency of tumor incidence in the MMTV-PyVmT mammary cancer model." (PMID 20808771, 2010). "However, among the tumor tissues from Grades 1, 2, and 3 of both LUADs and LUSCs, the NEDD9 levels remained similar." (PMID 40362444, 2025). "Also, NEDD9 over-expression caused hyper-proliferation of luminal cells and cooperated with the HER2 oncogene in tumor initiation." (PMID 38561760, 2024). "Meanwhile, IHC staining confirmed that the level of NEDD9 was reduced in shD-NEDD9 tumor tissue." (PMID 36604412, 2023). "NEDD9 is a molecule related to tumour invasion and metastasis." (PMID 35549691, 2022).
tumor (continued). "Exogenous overexpression of NEDD9 was reported to promote the epithelial-to-mesenchymal transition and enhance cellular migration and invasion, and was suggested as a candidate biomarker of tumor aggressiveness in human malignancies." (PMID 33710809, 2021). "To determine whether NEDD9 was required to maintain tumorigenic potential, we examined the effects of NEDD9 disruption and overexpression on tumor formation." (PMID 33710809, 2021). "In addition, in the lungs of aged OVX mice, there was a decrease of Nedd9 expression in the late stage of tumor progression, whereas in young mice the expression of this gene was not affected." (PMID 32887237, 2020). "Additionally, the applicability of the observed effects of Prdx1 on the NEDD9-Aurora A-HDAC6 signal axis to other tumor aspects requires future study." (PMID 32357862, 2020). "These can then bind to DNA again and play a transcription factor role for NEDD9 in tumor cells." (PMID 26011298, 2015). "The characterization of CSPG4 interaction with NEDD9 may provide insights for understanding mechanisms of growth and survival of these tumor stem cells." (PMID 22984505, 2012). "Notably, a significant reduction in tumor-invading cells, as measured in NEDD9+ cells, was detected in miRover tumors (P = 2.5×10−8 vs. Empty tumors)." (PMID 22869051, 2012). "Interestingly, although loss of Nedd9 in mouse models for other tumor types also slows tumor progression and improves survival, in the KPN mice analyzed in this study, tumor growth was enhanced by loss of NEDD9." (PMID 35410460, 2022). "Moreover, NEDD9 knockdown reduced the tumor incidence and delayed tumor progression in vivo." (PMID 33710809, 2021). "NEDD9 could serve as a biomarker of tumor aggression and a prognostic gene of solid cancers." (PMID 33344223, 2020). "The knock-out of murine Nedd9 led to a reduction in luminal progenitors, HER2 signaling, and tumor growth." (PMID 36831460, 2023). "Using a quantitative immunohistochemical (IHC) approach, we assessed the relationship between the NEDD9 expression levels and the stage of the disease in the cohort of primary NSCLC tumor samples (n = 16)." (PMID 35626121, 2022). "Some double-negative feedback loops, including miR-143 (LIMK1, SOX2) and miR-145 (ADAM17, NEDD9, SOX2), also result in miR-143 and miR-145 downregulation in tumor cells." (PMID 35205713, 2022). "Thus, miR-107 may control tumour progression by inhibiting the expression of NEDD9 in vivo." (PMID 35549691, 2022). "Based on the role of miRNAs in tumour development and the regulation of mRNAs, we used bioinformatics databases, including miRwalk, miRdb and TargetScan, to predict the upstream miRNAs that may regulate NEDD9, and we selected miR-103a-3p and miR-107 as candidates." (PMID 35549691, 2022). "When both NEDD9 and NOTCH signaling were inhibited, the expressions of CD90 and CD271 and tumor sphere formation induced by G-MDSCs were further abolished." (PMID 33710809, 2021). "As a marker of ESCC, NEDD9 maintained the stemness of ESCC cells and regulated CXCL8 through the ERK pathway to recruit MDSCs into the tumor, suggesting NEDD9 as a therapeutic target and novel prognostic marker for ESCC." (PMID 33710809, 2021). "The present study's significant finding is that miR-1252-5p functions as a tumor-suppressive miRNA in human PAC by inhibiting cell mobility, invasiveness, and proliferation via directly inhibiting its downstream target, NEDD9." (PMID 34314382, 2021). "Cell and animal experiments demonstrated that Prdx1 plays a role in regulation of the critical NEDD9-Aurora A-HDAC6 signal axis of cilium disaggregation and influences the tumor formation and invasion capacity of ESCC cells." (PMID 32357862, 2020).
tumor (continued). "Here, we demonstrated that the NEDD9-Aurora A-HDAC6 signal pathway plays an important role in cilium disaggregation and tumor invasion." (PMID 32357862, 2020). "NEDD9 acts as a scaffold to regulate SRC and focal adhesion kinase pathways to modulate tumor cell adhesion, invasion, migration, proliferation, apoptosis, and survival." (PMID 33344223, 2020). "Up-regulation of Nedd9 by TGF-beta is indeed required for proper actin rearrangements at the leading edge and efficient amoeboid motility of migrating tumour cells." (PMID 25606587, 2014). "The evidence of a functional role for Nedd9 in ErbB2-dependent tumourigenesis has been provided by the analysis of MMTV-ErbB2 mice with the genetic deletion of NEDD9, demonstrating that MMTV-ErbB2;Nedd9-null mice are strongly resistant to tumour formation." (PMID 25606587, 2014). "The levels of the tumor initiators HER2 and KRAS and metastasis genes VEGF, CXCL-4, CCL5, NEDD9 and RHoC were reduced in MCF-7 cells with UBE2C knockdown and increased with UBE2C overexpression." (PMID 24699941, 2014). "Mice null for Nedd9 are resistant to MMTV-polyoma T-induced tumorigenesis, recapitulating the significant role for NEDD9 in tumor development." (PMID 20825672, 2010). "The differential gene expression levels between the tumor and adjacent tissue indicated that the ROBO1, KLK6, LIMK2, KLK7, NLGN4X, MBP, and NEDD9 gene expression levels were higher in normal tissues than in tumors; however, EFNA1 was higher in the tumor than the normal ones." (PMID 38137332, 2023). "The Western blot and real-time PCR findings exhibited that the combination therapy reduced the expressions of Fzd7, Nedd9, VEGF-α, Vim and Mmp9 and upregulated E-Cad in 4T1 cells and liver and tumor tissues, thus preventing Wnt/β-catenin signaling and averting metastasis in TNBC." (PMID 36079579, 2022). "In addition, this carotenoid was reported to repress Wnt signaling via the down-expression of Wnt target genes, Fzd7, Nedd9 and Vim and the VEGF-α genes in 4T1 cells and mice tumor and lung tissues." (PMID 36079579, 2022). "These levels of SOX9 expression are able to trigger p21 but not sufficient to induce NEDD9 expression, resulting in suppression of tumor growth and metastasis." (PMID 30642390, 2019). "We found that the detection of NEDD9 in TCC of the bladder was significantly positively correlated with number of tumors, invasion depth, grade and stage, distant metastasis (p < 0.001), lymph node metastasis (p = 0.018), and tumor size (p = 0.004)." (PMID 28194179, 2017). "Additionally, NEDD9 was predicted to interact directly with the zinc finger protein 36 homolog (ZFP36), a tumor suppressor gene that negatively regulates NFκB." (PMID 27078000, 2016). "In addition, the miR-15a/miR-16-1 cluster upregulates several genes, including NEDD9, Snai2, MALAT1, and VEGF, and leads to the inhibition of tumor progression by enhancing tumor cell survival, metastasis, and the angiogenic properties of MM cells." (PMID 26649299, 2015). "In addition, we examined the mRNA expression levels of NEDD9 and GABBR1 in 10 matched-pairs NPC and adjacent non-tumor tissues by quantitative real-time PCR." (PMID 22880099, 2012). "Compared with adjacent non-tumor tissue, 10 of 11 NPC tumor biopsy samples showed a significant down-regulation of NEDD9 (P = 0.015)." (PMID 21283797, 2011). "Interestingly, NEDD9 can be significantly induced in tumor cells with high STAT3 levels, but not in tumor cells with low STAT3 levels." (PMID 37771106, 2023). "Note that this tumor incidence (~13.9%) corresponds to naturally occurring spontaneous mammary gland tumors documented in this strain, suggesting that NEDD9 is critical for the oncogenic activity of HER2, and without it, no tumors above naturally set background can arise." (PMID 36831460, 2023).
tumor (continued). "The NEDD9 protein does not have any known enzymatic functions but contains a domain that interacts with a variety of functional proteins, which play a significant role in the molecular signalling pathways related to tumour metastasis." (PMID 35549691, 2022). "Moreover, NEDD9 expression was significantly correlated with tumor invasion and differentiation, but not with tumor-node-metastasis (TNM) stage or lymph metastasis." (PMID 33710809, 2021). "Since loss of either Nedd9 or p130Cas/BCAR1 impairs growth of ErbB2 tumours, the full activation of crucial ErbB2 downstream effectors, such as Src and FAK, may require the co-expression of Nedd9 and p130Cas/BCAR1, suggesting that these two Cas proteins cooperate during early ErbB2 tumourigenesis." (PMID 25606587, 2014). "Furthermore, using the genotyping data and quantitative real-time PCR, they've identified several micro-deleted regions covering NEDD9 and GABBR1 genes and demonstrated that reduced expression of both genes in NPC tumor cells when compared to adjacent normal tissues." (PMID 22880099, 2012). "Previous studies have found that NEDD9 can activate the AKT/mTOR pathway and affect tumor progression, but no relevant studies have been reported in HCC." (PMID 39060928, 2024).
infection (8 papers, 2006 to 2025). The state of being infected such as from the introduction of a foreign agent such as serum, vaccine, antigenic substance or organism. "Next, we investigated the functional implications of NEDD9 loss in primary human macrophages by depleting NEDD9 using NEDD9-specific small interfering RNA followed by ST infection." (PMID 40506423, 2025). "In concordance with our in vitro data, Nedd9 loss significantly reduced ST burden in the spleens of mice compared to wildtype animals 4 days post infection." (PMID 40506423, 2025). "Complete loss of NEDD9 significantly reduced bacterial burden and enhanced inflammation upon ST infection both in vitro and in vivo." (PMID 40506423, 2025). "In contrast, NEDD9 clustered and colocalized with ST at 4 hours post infection and with lysosomal-associated membrane protein 1 (LAMP-1)." (PMID 40506423, 2025). "Next, we investigated how loss of Nedd9 regulates macrophage defense mechanisms upon ST infection." (PMID 40506423, 2025). "Consistently, we detected NEDD9 in lysates of isolated ST-containing phagosomes 4 h post infection of Nedd9wt/wt mBMDMs." (PMID 40506423, 2025). "Taken together, these data indicate that ST infection dynamically downregulates NEDD9 at both the mRNA and protein levels in a virulence independent manner." (PMID 40506423, 2025). "In line with this, measuring lysosomal ß-galactosidase activity on C12FDG confirmed lysosomal function is enhanced in Nedd9-/- BMDMs upon infection." (PMID 40506423, 2025). "Instead, inhibition of the lysosomal pathway resulted in stabilization of NEDD9 and increased bacterial burden in Nedd9-/- mBMDMs after ST infection." (PMID 40506423, 2025). "In this study, we observed that NEDD9 is downregulated transcriptionally and post-translationally in macrophages upon ST infection." (PMID 40506423, 2025). "Initially, we identified NEDD9 and known NEDD9 interaction partners being significantly downregulated in murine macrophages upon ST infection." (PMID 40506423, 2025). "In contrast, NEDD9 loss prevented this sharp increase in AKT phosphorylation in macrophages, particularly at 4 hours post ST infection, and resulted in significantly less AKT activation compared to wildtype controls." (PMID 40506423, 2025). "Here, we observed decreased levels of p62 in Nedd9-/- macrophages indicating enhanced lysosome-dependent autophagic flux upon infection." (PMID 40506423, 2025). "In our study, we observed that ST infection led to a change in the localization of NEDD9 from the cytosol to bacteria-containing phagosomes and eventually degraded in lysosomes." (PMID 40506423, 2025). "Consistent with our transcriptome and RNA data, we found NEDD9 significantly decreased at 4 hours post ST infection and almost completely depleted at 24 hours post infection." (PMID 40506423, 2025). "Collectively, these data suggest that in macrophages NEDD9 is degraded by the lysosomal machinery upon ST infection." (PMID 40506423, 2025). "In contrast, infection with different NEDD9 shRNAs significantly reduced NEDD9 in MDA-MB-231 and MDA-MB-231/4175 cells, while simultaneously suppressing cell invasion." (PMID 36604412, 2023). "Using real-time PCR, we observed that NEDD9 is down-regulated in miRover-NS compared to Empty-NS six days after infection (P = 0.0001)." (PMID 22869051, 2012). "While NEDD9 wildtype macrophages showed a tendency towards increased levels of total FAK and phosphorylated FAK Tyr397 (pFAK) after ST infection, loss of NEDD9 resulted in significantly decreased FAK and pFAK levels upon infection compared to wildtype controls." (PMID 40506423, 2025). "Since FAK and AKT signaling have been previously shown to regulate autophagy, we analyzed the conversion of LC-3 I-to II, a specific marker of autophagy, which we found to be significantly increased in Nedd9-/- macrophages upon infection compared to wildtype controls." (PMID 40506423, 2025).
infection (continued). "To assess the importance of NEDD9 in innate immune responses to bacterial infections, we reanalyzed a previously performed transcriptomics data analysis of wildtype mBMDMs 2 hours post ST infection and compared them to uninfected control cells." (PMID 40506423, 2025). "Notably, treatment with vacuolar ATPase inhibitor Concanamycin A significantly stabilized NEDD9 levels upon ST infection in mBMDMs." (PMID 40506423, 2025). "Therefore, we performed immunoblot analysis of Nedd9wt/wt and Nedd9-/- macrophages 1 hour and 4 hours post ST infection." (PMID 40506423, 2025). "To assess whether NEDD9 subcellular localization is altered upon infection, we performed immunofluorescence staining of ST infected Nedd9wt/wt and Nedd9-/- mBMDMs as well as human macrophages derived from PBMCs of healthy donors." (PMID 40506423, 2025). "To determine if these factors influenced control of NEDD9 expression, we next analyzed NEDD9 protein levels upon infection of mBMDM with ST Salmonella Pathogenicity Island SPI1 (ΔinvA) and SPI2 (ΔssaV) mutants, which have defects in the main type III secretion system (T3SS)." (PMID 40506423, 2025). "NEDD9 expression was strongly decreased in human macrophages 4 hours post ST infection." (PMID 40506423, 2025). "We show that NEDD9 translocates to phagolysosomes upon infection where it colocalizes with FAK." (PMID 40506423, 2025). "The fact that NEDD9 colocalized with bacteria-containing phagosomes including lysosomal marker LAMP1, as well as with pFAK upon ST infection and was downregulated via lysosomal degradation suggests a regulatory function in macrophage defense against bacteria." (PMID 40506423, 2025). "In line with our results and NEDD9 being well known to mediate FAK signaling, pFAK markedly colocalized with NEDD9 upon ST infection." (PMID 40506423, 2025). "Network analysis, siRNA knock down and RNAseq data identified new host signaling pathways under infection such as platelet-derived growth factor BB (PDGF BB) and neural precursor-cell-expressed developmentally down-regulated protein 9 (NEDD9)." (PMID 26175718, 2015). "In contrast, in our study, inhibition of the proteasomes did not alter the degradation of NEDD9 in macrophages after infection." (PMID 40506423, 2025). "If miR-18a-5p targets NEDD9 or related pathways, it may disrupt the use of viruses such as H5N1 for infection." (PMID 40266966, 2025). "The integrin signaling mediators BCAR1 and NEDD9, as well as MAPK3 and the SRC homology domain-containing protein SHC1, showed a strong, time-dependent phosphorylation after 90 min of infection, returning to control levels by 7 h post-infection." (PMID 25101063, 2014). "However, proteasome inhibition did not prevent NEDD9 degradation, implying a different degradation mechanism upon infection." (PMID 40506423, 2025). "However, neither the relevance of NEDD9 in cells of the innate immune system nor the role of NEDD9 in the response to infection has previously been systematically investigated." (PMID 40506423, 2025).